GNAS (GNAS complex locus)
Description:
Guanine nucleotide-binding proteins (G proteins) function as transducers in numerous signaling pathways controlled by G protein-coupled receptors (GPCRs). The alpha chain contains the guanine nucleotide binding site and alternates between an active, GTP-bound state and an inactive, GDP-bound state. Signaling by an activated GPCR promotes GDP release and GTP binding. The alpha subunit has a low GTPase activity that converts bound GTP to GDP, thereby terminating the signal. Both GDP release and GTP hydrolysis are modulated by numerous regulatory proteins. Signaling involves the activation of adenylyl cyclases, resulting in increased levels of the signaling molecule cAMP. Functions downstream of beta-adrenergic receptors. Stimulates the Ras signaling pathway via RAPGEF2. Guanine nucleotide-binding proteins (G proteins) function as transducers in numerous signaling pathways controlled by G protein-coupled receptors (GPCRs). The alpha chain contains the guanine nucleotide binding site and alternates between an active, GTP-bound state and an inactive, GDP-bound state. Signaling by an activated GPCR promotes GDP release and GTP binding. The alpha subunit has a low GTPase activity that converts bound GTP to GDP, thereby terminating the signal. Both GDP release and GTP hydrolysis are modulated by numerous regulatory proteins. Signaling involves the activation of adenylyl cyclases, resulting in increased levels of the signaling molecule cAMP. GNAS functions downstream of several GPCRs, including beta-adrenergic receptors. XLas isoforms interact with the same set of receptors as Gnas isoforms. May inhibit the adenylyl cyclase-stimulating activity of guanine nucleotide-binding protein G(s) subunit alpha which is produced from the same locus in a different open reading frame.
Synonyms: GNAS1; GSP; NESP55; NESP; GNASXL; GPSA; SCG6; SgVI; AHO; AIMAH1; C20orf45; GSA; PITA3; POH
Target class: Other membrane protein
Gene: Protein-coding gene on chromosome 20 (58,839,718 to 58,911,192, forward strand). Ensembl gene ENSG00000087460.
Subcellular location: Cell membrane; Cell projection, ruffle; Apical cell membrane; Cytoplasmic vesicle, secretory vesicle; Secreted
Subcellular location (Human Protein Atlas): Nucleoplasm; Cytosol; Plasma membrane
Pathways (Reactome):
Signal Transduction: G alpha (i) signalling events; G alpha (s) signalling events; G alpha (z) signalling events; GPER1 signaling; Glucagon-type ligand receptors; Hedgehog 'off' state
Metabolism: Glucagon signaling in metabolic regulation; Glucagon-like Peptide-1 (GLP1) regulates insulin secretion; PKA activation in glucagon signalling
Cellular responses to stimuli: High laminar flow shear stress activates signaling by PIEZO1 and PECAM1:CDH5:KDR in endothelial cells
Disease: ADORA2B mediated anti-inflammatory cytokines production
Hemostasis: Prostacyclin signalling through prostacyclin receptor
Transport of small molecules: Vasopressin regulates renal water homeostasis via Aquaporins
Gene Ontology:
Molecular function: protein binding; adenylate cyclase activator activity; beta-2 adrenergic receptor binding; corticotropin-releasing hormone receptor 1 binding; D1 dopamine receptor binding; G-protein beta/gamma-subunit complex binding; GTPase activity; insulin-like growth factor receptor binding; ionotropic glutamate receptor binding; mu-type opioid receptor binding; GTP binding; guanyl nucleotide binding
Biological process: adenylate cyclase-activating G protein-coupled receptor signaling pathway; bone development; developmental growth; platelet aggregation; adenylate cyclase-activating dopamine receptor signaling pathway; positive regulation of cold-induced thermogenesis; renal phosphate excretion; sensory perception of chemical stimulus; G protein-coupled receptor signaling pathway; signal transduction
Cellular component: apical plasma membrane; cytosol; extracellular exosome; membrane; plasma membrane
Genetic constraint (gnomAD): Loss-of-function variants: 6 observed, 39.25 expected, observed/expected ratio (o/e) 0.15, 90% interval 0.083 to 0.3. The upper end of that interval is the gene's LOEUF score, 0.3, which puts it in group 1 of 6, group 1 being the genes least tolerant of losing a copy. Missense variants: 151 observed, 424.06 expected, observed/expected ratio (o/e) 0.36, 90% interval 0.31 to 0.41. Synonymous variants: 178 observed, 160.29 expected, observed/expected ratio (o/e) 1.11, 90% interval 0.98 to 1.26.
Cancer hallmarks: proliferative signalling (promotes); suppression of growth (promotes)
Homologues: Orthologues: macaque GNAS (100% identical), chimpanzee GNAS (94% identical), dog GNAS (94% identical), mouse Gnas (93% identical), rat Gnas (93% identical), guinea pig GNAS (83% identical), zebrafish gnas (81% identical), Caenorhabditis elegans gsa-1 (65% identical), Drosophila melanogaster Galphai (39% identical), Caenorhabditis elegans gpa-16 (39% identical), Caenorhabditis elegans gpa-4 (37% identical), Drosophila melanogaster CG30054 (36% identical), and 13 more. Paralogues in human: GNAL (72% identical), GNAO1 (41% identical), GNAI2 (40% identical), GNAT3 (40% identical), GNA11 (39% identical), GNAT2 (39% identical), GNA14 (39% identical), GNAI1 (39% identical), GNAI3 (39% identical), GNAQ (39% identical), GNAT1 (38% identical), GNAZ (38% identical), and 3 more.
Diseases named in the same sentence as GNAS in open-access papers:
GNAS is named in the same sentence as 345 diseases in open-access papers, as found by Europe PMC text mining. Sharing a sentence is not in itself a finding about the gene and the disease. The quoted sentences say what the papers report.
pseudohypoparathyroidism (81 papers, 2007 to 2025). "ASD has since been reported as a phenotypic feature of acrodysostosis type 2 (associated with PRKAR1A and PDE4D genes) and pseudohypoparathyroidism (associated with GNAS gene)." (PMID 40917827, 2025). "The novel splice site variant expands the mutational spectrum of GNAS-related disorders and highlights the phenotypic consistency among individuals with molecularly confirmed pseudohypoparathyroidism." (PMID 41155848, 2025). "Two were diagnosed with pseudohypoparathyroidism due to GNAS mutations and one with acrodysostosis caused by a PRKAR1A variant." (PMID 41155848, 2025). "Two patients were diagnosed with pseudohypoparathyroidism and carried heterozygous mutations in the GNAS gene." (PMID 41155848, 2025). "Two cases harbored heterozygous GNAS mutation, including a novel splice site variant (c.719-30A>T), compatible with pseudohypoparathyroidism, and one had a heterozygous PRKAR1A mutation, compatible with acrodysostosis." (PMID 41155848, 2025). "Pseudohypoparathyroidism (PHP) is a rare disorder caused by defects in the GNAS gene, which encodes the alpha subunit of the stimulatory G protein (Gsα) (Jüppner, 2021)." (PMID 40893942, 2025). "Approximately 70-80% of individuals with pseudohypoparathyroidism type 1a have a clearly identifiable genetic cause, predominantly attributed to GNAS Complex Locus (GNAS) gene mutations or methylation changes." (PMID 39095891, 2024). "Defects of the GNAS gene have been associated with different phenotypes such as pseudohypoparathyroidism Ia, Ib, and Ic (PHP-Ia, -Ib, -Ic), pseudopseudohypoparathyroidism (PPHP), progressive osseous heteroplasia (POH), and osteoma cutis (OC)." (PMID 39456695, 2024). "For example, patients with pseudohypoparathyroidism, which is associated with inactivating mutations in the GNAS gene encoding the alpha subunit of the G protein, often demonstrate foci of heterotopic ossification in subcutaneous fat." (PMID 36359914, 2022). "A large number of reports have confirmed that GNAS mutations can cause pseudohypoparathyroidism (PHP), congenital hypothyroidism (CH) and growth hormone deficiency (GHD) due to hormone resistance." (PMID 35927642, 2022). "Pseudohypoparathyroidism type 1a (PHP1a) is a genetic disorder caused by heterozygous loss-of-function mutations on the maternal allele of the GNAS gene." (PMID 35497370, 2022). "Herein, we report a case of Fahr syndrome which allowed the diagnosis of very rare GNAS mutation in familial pseudohypoparathyroidism type 1a." (PMID 35600030, 2022). "GNAS (guanine nucleotide binding protein, alpha stimulating activity polypeptide) causes pseudohypoparathyroidism when mutated." (PMID 34249923, 2021). "Pseudohypoparathyroidism (PHP) represents a heterogeneous group of rare endocrine disorders caused by (epi) genetic abnormalities affecting the GNAS locus." (PMID 33663571, 2021). "Inactivating loss-of-function mutations in GNAS cause pseudohypoparathyroidism type 1a (PHP1A), pseudopseudohypoparathyroidism, and progressive osseous heteroplasia." (PMID 33530447, 2021). "Loss-of-function mutations or epigenetic alterations of GNAS are responsible for different human diseases that involve abnormal skeletal development, metabolism, and hormone actions, such as pseudohypoparathyroidism Ia (MIM: 103580)." (PMID 34220953, 2021). "For example, the GNAS mutations causing pseudohypoparathyroidism type-1a are inherited maternally and, therefore, disrupt one copy of Gsα without affecting XLαs." (PMID 34220953, 2021). "The proband with a GNAS mutation, a female 12 and 9/12 years of age, was diagnosed with pseudohypoparathyroidism Ia." (PMID 34740356, 2021). "The second frequently identified genetic obesity disorders were biallelic LEPR pathogenic variants (6/37), followed by GNAS pathogenic variants leading to pseudohypoparathyroidism type 1a (5/37)." (PMID 32384097, 2020).
pseudohypoparathyroidism (continued). "Pseudohypoparathyroidism type 1a (Albright's hereditary osteodystrophy) due to GNAS mutations involves generalized hormone resistance (PTH, TSH, FSH, and LH), short stature, and various skeletal anomalies." (PMID 31320908, 2019). "Pseudohypoparathyroidism is one of the disorders associated with GNAS locus deficit, and the GNAS locus is associated with RPTC responses to parathyroid hormone and electrolyte balance." (PMID 28715443, 2017). "Pseudohypoparathyroidism (PHP) is a rare endocrine disorder that can be caused by genetic or epigenetic alterations in the imprinted cluster GNAS localized on chromosome 20q13.3." (PMID 26819647, 2016). "Genetic testing revealed a known mutation of GNAS gene, confirming the diagnosis of Pseudohypoparathyroidism Type Ia (PHP-Ia) (c.34C>T (p.G1n12X))." (PMID 27703483, 2016). "Pseudohypoparathyroidism (PHP) is caused by reduced expression of genes within the GNAS cluster, resulting in parathormone resistance." (PMID 25005734, 2015). "Loss of the orthologous GNAS transcript in humans is associated with a number of endocrine and bone disorders including pseudohypoparathyroidism, Albright Hereditary Ostedystrophy and progressive osseous heteroplasia." (PMID 23822972, 2013). "Pseudohypoparathyroidism type Ia (PHP-Ia) is due to maternal inheritance of an inactivating mutation in GNAS and pseudohypoparathyroidism type Ib is caused by defective imprinting at the cluster." (PMID 23822972, 2013). "These murine phenotypes largely reproduce the symptoms of a human genetic disorder of maternally inherited GNAS mutations, termed ‘Albright's Hereditary Osteodystrophy / Pseudohypoparathyroidism type Ia (AHO/PHP-Ia)’." (PMID 22253771, 2012). "This disease continuum may encompass both forms of acrodysostosis (caused by PRKAR1A and PDE4D variants), Albright hereditary osteodystrophy, and pseudohypoparathyroidism (caused by GNAS variants)." (PMID 40917827, 2025). "Loss of function mutations of GNAS cause pseudohypoparathyroidism." (PMID 39595984, 2024). "Additionally, GNAS, the gene responsible for encoding the Gsα subunit and implicated in pseudohypoparathyroidism, has been associated with dental anomalies such as enamel hypoplasia, delayed tooth eruption, and craniofacial bone malformations." (PMID 39519162, 2024). "One case was homozygous for the HBA2 variant [NM_000517.6: c.377T>C(p.Leu126Pro)], which was inherited from both parents, and was diagnosed with alpha thalassemia; the other patient carried a de novo GNAS variant [NM_000516.7: c.139G>A(p.Gly47Ser)] and was diagnosed with pseudohypoparathyroidism Ia." (PMID 38764027, 2024). "Defects of the GNAS gene have been mainly associated with pseudohypoparathyroidism Ia." (PMID 39456695, 2024). "Moreover, abnormal methylation in the GNAS gene has been associated with disruption of several phenotypes, including diseases such as pseudohypoparathyroidism and obesity in humans." (PMID 35562812, 2022). "In addition, GNAS germline mutations are related to different types of pseudohypoparathyroidism (PHP-Ia,-Ib,-Ic) and pseudopseudohypoparathyroidism (PPHP)." (PMID 36035165, 2022). "Furthermore, inactivating mutations in the maternal allele of GNAS gene, coding for the binding protein Gαs, cause Pseudohypoparathyroidism type IA, also known as Albright hereditary osteodystrophy (AHO)." (PMID 33919228, 2021). "GNAS is mutationally activated in various cancer types, such as growth hormone-secreting pituitary tumors, pancreatic cancer and colorectal cancer, while has inactivating mutations in pseudohypoparathyroidism type 1a." (PMID 34722286, 2021). "PTH resistance of pseudohypoparathyroidism may be transient as in the case of renal dysplasia or obstructive uropathy or permanent because of GNAS mutations." (PMID 31320908, 2019). "Pseudohypoparathyroidism (PHP) is caused by (epi)genetic defects in the imprinted GNAS cluster." (PMID 26819647, 2016).
pseudohypoparathyroidism (continued). "Alternative first exons for GNAS transcripts lead to distinct products, which in human have been linked to osteodystrophy and pseudohypoparathyroidism phenotypes, while in mouse GNAS heterozygous mutants show metabolic abnormalities and insulin hypersensitivity (see Glycolysis above)." (PMID 17244347, 2007). "Pseudohypoparathyroidism type 1A (PHP1A) is caused by maternally inherited mutations or epigenetic alterations in the GNAS gene, which encodes the stimulatory G protein α-subunit (Gsα)." (PMID 41155848, 2025). "Inactivating genetic and epigenetic changes in GNAS, leading to Gsα deficiency, are known to be associated with several disorders, including different variants of pseudohypoparathyroidism, which may feature severe, early-onset obesity as part of their clinical manifestations." (PMID 39684386, 2024). "Maternally inherited GNAS mutations cause Albright hereditary osteodystrophy (AHO) and pseudohypoparathyroidism type 1A, whereas paternally inherited mutations cause AHO alone." (PMID 37628941, 2023). "On the other hand, in the related disorder pseudopseudohypoparathyroidism (PPHP), mutations in the GNAS locus occur, which are usually paternally inherited and are designated as non-AHO." (PMID 32647264, 2020). "Loss-of-function GNAS mutations classically lead to Albright's Hereditary Osteodystrophy (AHO) and pseudohypoparathyroidism, often with significant effects on bone formation and mineral metabolism." (PMID 27579188, 2016). "Pseudohypoparathyroidism (PHP), characterized by parathyroid hormone resistance, can result from heterozygous LOF variants of the gene encoding the Gαs subunit, GNAS, located at chromosome 20q13." (PMID 39743506, 2025). "Small germline microdeletions, microinsertions, and chromosomal rearrangements within GNAS occur in patients with pseudohypoparathyroidism type 1a and type 1b." (PMID 40414875, 2025). "Despite the thorough analysis, no known pathogenic variants were found in genes typically associated with Fahr’s syndrome (e.g., XRP1, PDGFRB, JAM2, PDGFB, SLC20A2, or MYORG) or pseudohypoparathyroidism (e.g., GNAS, STX16, or GNASAS1)." (PMID 39519162, 2024). "Heterozygous Gsα-inactivating mutations lead to obesity in patients with pseudohypoparathyroidism type 1A (PHP1A) and in mice, but only when the mutation is on the maternal allele due to tissue-specific imprinting of GNAS/Gnas, the gene encoding Gsα." (PMID 38175730, 2024). "Pseudohypoparathyroidism (PHP) is a series of diseases related to pathological changes and neurocognitive and endocrine abnormalities, mainly due to the GNAS mutation on chromosome 20q13.2, which weakens receptor‐mediated hormone signal transduction." (PMID 36669868, 2023). "Mutations on GNAS, NESP55, and STX16 genes are associated with pseudohypoparathyroidism (PHP), a rare disease inherited in an autosomal dominant pattern." (PMID 35163424, 2022). "Disorders of GNAS inactivation produce several different clinical phenotypes including pseudohypoparathyroidism (PHP), pseudopseudohypoparathyroidism (PPHP), progressive osseous heteroplasia (POH), and osteoma cutis (OC)." (PMID 35296306, 2022). "Pseudohypoparathyroidism (PHP) encompasses a highly heterogenous group of disorders, characterized by parathyroid hormone (PTH) resistance caused by mutations in the GNAS gene or other upstream targets." (PMID 35410271, 2022). "Pseudohypoparathyroidism (PHP) is a rare endocrine disorder derived from the defective activation of the cAMP pathway by the parathyroid hormone secondary to GNAS molecular defects." (PMID 31555217, 2019). "Pseudohypoparathyroidism (PHP) is a rare and inherited disease caused by mutations in the GNAS-gene or upstream of the GNAS complex locus." (PMID 31892351, 2019). "Pseudohypoparathyroidism (PHP) is caused by loss-of-function mutations at the GNAS gene (as in the PHP type 1A; PHP1A), de novo or inherited at heterozygous state, or by epigenetic alterations at the GNAS locus (as in the PHP1B)." (PMID 38664677, 2024).